RNU6-1262P (RNA, U6 small nuclear 1262, pseudogene)
Gene: Small nuclear RNA gene on chromosome 16 (68,284,223 to 68,284,318, reverse strand). Ensembl gene ENSG00000252026.
Homologues: Orthologues: chimpanzee U6 (99% identical), macaque U6 (94% identical), dog U6 (72% identical). Paralogues in human: RNU6-380P (80% identical), RNU6-703P (78% identical), RNU6-1130P (77% identical), RNU6-205P (77% identical), RNU6-1203P (76% identical), RNU6-1249P (76% identical), RNU6-628P (76% identical), RNU6-657P (76% identical), RNU6-1266P (75% identical), RNU6-15P (75% identical), RNU6-21P (75% identical), RNU6-238P (75% identical), and 1283 more.